KRAS (KRas proto-oncogene, GTPase)
Diseases named in the same sentence as KRAS in open-access papers (continued):
Sharing a sentence is not in itself a finding about the gene and the disease.
Splenomegaly (8 papers, 2016 to 2024). Abnormal increased size of the spleen. "We arrived at a JMML diagnosis after observing leukocytosis, less than 20% blast cells in the peripheral blood and bone marrow, increased monocyte counts, negativity for the BCR-ABL fusion gene, positivity for somatic KRAS mutation, and massive splenomegaly." (PMID 33327329, 2020). "For example, somatic mutation in NRAS or KRAS genes in hematopoietic cells can cause a rare autoimmune disorder, characterized by lymphadenopathy and splenomegaly due to abnormal expansion of lymphocytes." (PMID 28736556, 2017). "Clinically, CBL mutations were associated with a more proliferative phenotype evidenced by increased bone marrow blasts, leukocytosis and splenomegaly, similar to other RAS pathway mutations such as KRAS, NRAS and PTPN11." (PMID 39298477, 2024). "Clinically, CBL mutations were associated with increased bone marrow blasts at diagnosis, leukocytosis and splenomegaly, similar to patients harboring NRAS or KRAS mutations." (PMID 39298477, 2024).
thymoma (8 papers, 2021 to 2026). A neoplasm arising from the epithelial cells of the thymus. "Additionally, the authors documented AKT3, ALK, CSF1R, FGFR4, KRAS, NRAS, and PIK3CA as common mutated genes in thymomas." (PMID 38338833, 2024). "Significant enrichment of mutated genes of the RAS and PI3K-Akt signalling pathways was reported in thymomas (AKT3, ALK, CSF1R, FGFR4, KRAS, NRAS, HRAS, PIK3CA), and their role in thymoma development was suggested." (PMID 35884448, 2022). "Gene mutations previously reported in type A and AB thymoma (e.g., GTF2I, HRAS, KRAS) were not identified in our cohort." (PMID 41344988, 2026). "A study from our center revealed that serum levels of KRAS and SLEP were elevated in patients with thymoma with MG, both of which significantly decreased after docetaxel treatment, possibly related to improvement in MG and control of thymoma." (PMID 41487432, 2025).
thyroid tumor (8 papers, 2012 to 2026). A benign or malignant neoplasm affecting the thyroid gland. "In one such study, 52% of thyroid tumor specimens carried clinically relevant mutations in at least one screened gene, most frequently involving KRAS (86%), followed by NRAS (7%), BRAF (6%), and combined NRAS + BRAF mutations (2%)." (PMID 41595518, 2026). "Human thyroid tumors are often characterized by activating point mutations in BRAF, NRAS, HRAS, or KRAS, leading to the overactivation of MAPK- and mTOR-signaling pathways." (PMID 40711277, 2025). "In contrast, in human medicine, the molecular characterization of thyroid tumor-ascertained mutations in BRAF, NRAS, HRAS, and KRAS is relevant as they are players implicated in thyroid tumor progression through their activation of MAPK- and mTOR-signaling pathways." (PMID 40711277, 2025). "There are 3 isoforms of RAS: HRAS, KRAS and NRAS found in thyroid tumours." (PMID 27703585, 2016).
arteriovenous malformations (7 papers, 2022 to 2026). "Within 4 of 11 (36%) individuals with fast-flow lesions (arteriovenous malformations [AVM]) we identified somatic variants in KRAS and MAP2K1 with VAFs ranging from 1.27% to 9.98%." (PMID 39669602, 2024). "PIK3CA variants were found in 67% of Klippel Trenaunay Syndrome individuals; KRAS variants in 60% of arteriovenous malformations; MET was mutated in 75% of lymphovenous malformations." (PMID 35807022, 2022). "Here, we identified a putative new tumor type characterized by the same dural location, a similar histopathological pattern and a frequent GJA4 p.Gly41Cys mutation (3/6 cases), distinct from genes implicated in CCM (CCM1/2/3, MAP3K3, PIK3CA) and arteriovenous malformations (KRAS) of the brain." (PMID 35642047, 2022). "Recently, low‐frequency somatic KRAS mutations were detected in human sporadic bAVMs,4, 5, 6, 7, 8 and in vivo experiments have confirmed that KRAS mutation can drive abnormal vascular morphology and arteriovenous malformation (AVM) development in mouse and zebrafish models." (PMID 36718590, 2023). "We based our approach on previously published studies that modeled KRAS-induced arteriovenous malformations (AVMs) by treating cells with a control vector or a vector expressing mutant KRAS." (PMID 37842094, 2023).
chronic obstructive pulmonary disease (7 papers, 2016 to 2025). A chronic and progressive lung disorder characterized by the loss of elasticity of the bronchial tree and the air sacs, destruction of the air sacs wall, thickening of the bronchial wall, and mucous accumulation in the bronchial tree. "Prior pulmonary disease history in patients, such as chronic obstructive pulmonary disease (COPD), was shown to be irrelevant to KRAS mutation in a study on 325 NSCLC patients, however there is insufficient evidence to support this claim." (PMID 36899885, 2023). "Smoking is a significant environmental factor linked to KRAS mutations in LUAD patients and increased ADAM9 expression in individuals with chronic obstructive pulmonary disease." (PMID 40429751, 2025).
diffuse large B-cell lymphoma (7 papers, 2012 to 2025). "Additionally, oral administration of CUDC-907 at a dose of 100 mg/Kg induced tumor regression or stability in Daudi non-Hodgkin lymphoma, SU-DHL-4 diffuse large B-cell lymphoma (DLBCL), and KRAS-mutant A549 NSCLC xenografts with decent tolerance." (PMID 33147762, 2020).
dilated cardiomyopathy (7 papers, 2010 to 2025). Cardiomyopathy which is characterized by dilation and contractile dysfunction of the left and right ventricles. "However, these adult mice displayed dilated cardiomyopathy, indicating that KRAS has a unique role in cardiovascular homeostasis and that the mortality of KRAS-deficient mice is likely derived from the inability of other RAS proteins to be expressed in the same subcellular compartments." (PMID 31681616, 2019). "These mice were viable but had dilated cardiomyopathy, suggesting that HRAS cannot fully replace KRAS, but that in this context, KRAS may be dispensable." (PMID 41248180, 2025). "Whereas KRAS knockout resulted in embryonic lethality, a subsequent study inserted HRAS into the endogenous KRAS locus, resulting in normal embryonic development, but induced dilated cardiomyopathy during adulthood." (PMID 25109951, 2014).
endometrioid tumor (7 papers, 2013 to 2025). A benign, borderline, or malignant epithelial tumor of the female reproductive system characterized by the presence of glands and/or cysts lined by neoplastic cells that resemble endometrial cells. "In detail, two endometrioid tumors with a PIK3R1 mutation had a coexisting PTEN mutation, and one of them also had a mutation in the KRAS gene." (PMID 39858051, 2025). "Because KRAS mutations can stimulate PI3K activity and were observed in 16% (4/25) of endometrioid tumors, the frequency of the PI3K pathway aberration due to PIK3R1, PIK3CA, PTEN, and KRAS mutations may increase to 60% (15/25) in this histotype." (PMID 39858051, 2025). "Other altered genes labelling the endometrioid cancer were CTNNB1, KRAS, POLE, and ARID1A genes, each of them accepted as genetic biomarker of the endometrioid tumors." (PMID 36010253, 2022).
epilepsy (7 papers, 2015 to 2025). A brain disorder characterized by episodes of abnormally increased neuronal discharge resulting in transient episodes of sensory or motor neurological dysfunction, or psychic dysfunction. "This study also found that bAVMs with somatic KRAS mutations were prone to rupture, and bAVM patients with certain 16 de novo mutations were found to exhibit epilepsy as the first presenting symptom." (PMID 39200259, 2024). "This is the first reported association of a KRAS genetic variant with cortical malformations associated with epilepsy, and suggests a possible genetic substrate for hippocampal sclerosis." (PMID 34208656, 2021). "This is the first documented KRAS mutation in a brain specimen of cortical malformation related to epilepsy." (PMID 34208656, 2021). "Here, we report a Chinese infant LNSS patient with intermittent epilepsy and ocular pterygium who has a KRAS G12D mosaic mutation, which was detected by performing next-generation sequencing on a noninvasively collected skin lesion sample." (PMID 26521233, 2015). "That the KRAS mutation was present only in the removed pathological brain and skin tissue, and not in the blood, is concordant with the hypothesis that this mutation might be linked to the epilepsy in this case." (PMID 34208656, 2021). "Regarding the KRAS G12D mutation we report here, the patient was clinically diagnosed with LNSS and displayed linear nevus sebaceous, eye lesions and epilepsy, in contrast with the previously reported NS cases." (PMID 26521233, 2015).
Ewing sarcoma (7 papers, 2014 to 2024). A small round cell tumor that lacks morphologic, immunohistochemical, and electron microscopic evidence of neuroectodermal differentiation. "KRAS G12D mutation was present in 23 patients overall – 16 patients in the STS cohort, four patients in the uterine sarcoma cohort, one patient in the bone sarcoma cohort (Ewing sarcoma), one patient in the breast sarcoma cohort (malignant phyllodes tumor), and one patient in the GIST cohort." (PMID 36741731, 2022).
neuroendocrine carcinoma (7 papers, 2019 to 2026). A malignant neuroendocrine neoplasm composed of cells containing secretory granules that stain positive for NSE and chromogranin.
pilocytic astrocytoma (7 papers, 2020 to 2025). Pilocytic astrocytoma is a rare subtype of low-grade glioma of the central nervous system characterized by a well circumscribed, often cystic, brain tumor with a discrete mural nodule and long, hair-like projections that extend from the neoplastic astrocytes. "There are also increased chances of mutations of BRAF, constant chromosome gains at 7q34, and mutations of KRAS activating the MAPK pathway in sporadic pilocytic astrocytoma." (PMID 35888021, 2022). "In one pilocytic astrocytoma, the genes PTPN11, NRAS, KRAS, and HRAS were activated and somatic G12A KRAS mutations were found in Pas." (PMID 37675821, 2023).
polyp (7 papers, 2017 to 2024). A usually exophytic mass attached to the underlying tissue by a broad base or a thin stalk. "The relative increase in abundance of Ruminococcus gnavus in polyp patients agrees with studies that found a positive association between R. gnavus and KRAS mutations in aberrant crypt foci, which are very early dysplastic clusters that can form neoplasms." (PMID 37894412, 2023). "In patient 2, although KRAS mutations were found in both the polyp and carcinoma, the mutation alleles were G12D and G12C in the polyp and G13D in the carcinoma, which all have been confirmed by Sanger sequencing." (PMID 29069792, 2017). "In contrast to the conventional pathway, characterized by KRAS mutations, CIN, CIMP negative, and MSS, the progression from serrated polyp toward cancer seems driven and featured by alternative molecular imprints, with different prognostic significance." (PMID 31330830, 2019).
pseudomyxoma peritonei (7 papers, 2004 to 2025). An appendix cancer that is characterized by progressive accumulation of mucus-secreting tumor cells within the abdomen and pelvis. "Examinations of pseudomyxoma from the appendix revealed that KRAS and GNAS pathogenic mutations are prevalent genetic characteristics of pseudomyxoma peritonei." (PMID 38672528, 2024). "Molecular analyses of appendiceal pseudomyxoma showed that KRAS and GNAS pathogenic variants are common genetic features of pseudomyxoma peritonei." (PMID 35255903, 2022). "Molecular analyses of pseudomyxoma from the appendix showed that KRAS and GNAS pathogenic variants are common genetic features of pseudomyxoma peritonei." (PMID 35255903, 2022). "In pseudomyxoma peritonei (PMP), KRAS and GNAS mutations are frequent." (PMID 37509688, 2023).
sarcomatoid carcinoma (7 papers, 2014 to 2025). A malignant epithelial neoplasm characterized by the presence of spindle cells and anaplastic morphologic features. "A substantial group of sarcomatoid carcinomas has been reported to belong to the first cluster and carries KRAS mutation and high PD-L1 expression." (PMID 40423070, 2025). "Three (37.5%) KRAS mutations were detected in sarcomatoid carcinoma." (PMID 26486077, 2015). "Eight sarcomatoid carcinoma were analyzed for the presence of EGFR kinase domain mutations, KRAS mutations, HER2 kinase domain mutations, BRAF mutations, ALK fusions, RET fusions and AKT1 mutations." (PMID 26486077, 2015). "PSC exhibits high KRAS and EGFR mutation rates, and spindle cell carcinoma has a worse prognosis." (PMID 39720986, 2025).
small bowel adenocarcinoma (7 papers, 2020 to 2025). "Briefly, KRAS was the popular gene for mutation analysis ranging from 0% mutation in squamous cell anal carcinoma to 57% in small intestinal adenocarcinoma." (PMID 33127962, 2020). "Correlation between clinicopathologic factors and HES-1 expression based on KRAS genotype in small intestinal adenocarcinoma patients." (PMID 32974155, 2020). "Further studies are needed to clarify the relationship between HES-1 and KRAS genotype in small intestinal adenocarcinomas." (PMID 32974155, 2020). "In addition, we examined the potential clinical significance of HES-1 expression in patients with small intestinal adenocarcinomas harboring mutant KRAS." (PMID 32974155, 2020). "Materials and Methods: To investigate the clinicopathologic and prognostic implications of HES-1, HES-1 immunohistochemical expression was analyzed in digital images along with clinicopathological variables, including survival and KRAS genotype, in 185 small intestinal adenocarcinomas." (PMID 32974155, 2020).
vascular malformation (7 papers, 2020 to 2025). A non-neoplastic disorder that is the result of defects of vascular morphogenesis. "And recurrently mutated genes were identified in several vascular malformations as well including TEK/TIE2 mainly in venous malformations, GNA11/14 mainly in vascular tumors, KRAS/NRAS/RASA1/HRAS mainly in AVMs, GNAQ, IDH1/2, AKT1, PTEN and PIK3CA." (PMID 34736485, 2021). "Furthermore, atypical variants in some oncogenes are (almost) exclusively found in vascular malformations (e.g. atypical HRAS and KRAS indel variants)." (PMID 38778413, 2024). "The identified PIK3CA mutations have been previously reported in other patients with PROS, and the KRAS and TEK mutations in patients with vascular malformation, but the MAP2K3 and TBC1D4 mutations have not been previously reported." (PMID 36175890, 2022).
anemia (6 papers, 2008 to 2025). A reduction in the number of red blood cells, the amount of hemoglobin, and/or the volume of packed red blood cells. "The KRAS gene is crucial for normal mouse development, and KRAS knockout was found to be lethal in mice due to severe anemia and severe hepatic injury." (PMID 39857784, 2025).
autoimmune lymphoproliferative syndrome (6 papers, 2014 to 2021). Autoimmune lymphoproliferative syndrome (ALPS) is a rare, inherited disorder characterized by non-malignant lymphoproliferation, multilineage cytopenias, and a lifelong increased risk of Hodgkin's and non-Hodgkin's lymphoma. "RALD was initially classified into the type IV of autoimmune lymphoproliferative syndrome (ALPS) caused by KRAS/NRAS mutation." (PMID 31412876, 2019). "Furthermore, patients with autoimmune lymphoproliferative syndrome (ALPS) have been shown to carry somatic or germline mutations in the genes that encode FAS, Fas-ligand, caspase 10, caspase 8, NRAS, and KRAS." (PMID 32121251, 2020).
B cell lymphoma (6 papers, 2010 to 2024). "Finally, the relapsed tumors acquired a number of mutations in genes not typically altered in B-cell lymphomas such as KRAS, MAP2K2, PIK3R1, and PIK3R2, further supporting their loss of B-cell identity and suggesting that targeting PI3K and KRAS in such cases may prove therapeutically effective." (PMID 38638855, 2024).
bladder tumor (6 papers, 2018 to 2025). "Among them, 13 genes, including AHR, BCL2L1, CCND1, KRAS, SOX4, MYC, and E2F family genes, were previously reported to have increased expression in BC tissue, and their alterations, either through amplification or upregulation, are linked with bladder tumor initiation or progression." (PMID 40801146, 2025).
cervical squamous cell carcinoma (6 papers, 2017 to 2023). A squamous cell carcinoma arising from the cervical epithelium. "ERBB2 mutations concomitantly harbored PIK3CA or KRAS mutations were found in non-squamous cervical cancer." (PMID 32922530, 2020).
clear cell renal cell carcinoma (6 papers, 2020 to 2024). "NGS analyses revealed KRAS gene mutation (c.35G > T/p.G12V in exon 2) in the papillary renal neoplasm with reverse polarity, with PIK3CA gene mutation restricted to the clear cell renal cell carcinoma (c.1624G > A/p.E542K in exon 10)." (PMID 33023600, 2020).
ganglioglioma (6 papers, 2018 to 2026). A well differentiated, slow growing neuroepithelial neoplasm composed of neoplastic, mature ganglion cells and neoplastic glial cells. "Mutations in KRAS were revealed in three tumours: an anaplastic astrocytoma, IDH-wildtype; an anaplastic oligodendroglioma, IDH-mutant with a 1p/19q codeletion; and a ganglioglioma." (PMID 34525976, 2021).
Hyperglycemia (6 papers, 2014 to 2025). An increased concentration of glucose in the blood. "The impact of KRAS-related non-coding RNAs on cellular activities has also been assessed in the context of hyperglycemia and cardiac hypertrophy." (PMID 35139853, 2022). "In T3M4 cells, a massive (more than 5-fold) increase in phosphorylated ERK1/2 in parallel with a significant increase in p21 protein production were found after exposures both to hyperglycemia and to the PSC-CCM, despite that the T3M4 is a KRAS-Wild type ductal PaC cell line." (PMID 26010611, 2015).